EGF (epidermal growth factor)
Diseases named in the same sentence as EGF in open-access papers (continued):
Sharing a sentence is not in itself a finding about the gene and the disease.
periodontitis (10 papers, 2014 to 2025). An acute or chronic inflammatory process that affects the tissues that surround and support the teeth. "Rs2237051 and rs4444903 are two common SNPs of EGF gene, and show close association with genetic susceptibility of inflammatory diseases, including periodontitis." (PMID 34592884, 2021). "Considering the genetic association of epidermal growth factor (EGF) gene polymorphisms with the susceptibility of periodontitis, its genetic association with peri-implantitis risk in a Chinese Han population was explored." (PMID 34592884, 2021). "A previous study has reported the association between another intron-specific locus of EGF and severe chronic periodontitis." (PMID 32477838, 2020). "EGF and its receptor are also implicated in periodontitis, but little is known about the regulation of the EGF pathway during periodontitis." (PMID 28748038, 2017). "Additionally a single nucleotide mutation within the EGF coding sequence was associated with the development of severe chronic periodontitis." (PMID 28748038, 2017). "Our results are, to the best of our knowledge, the first to show low EGF serum levels in individuals with periodontitis." (PMID 39101637, 2024). "Interestingly, the periodontitis-associated pathogen P. gingivalis has been shown to inhibit EGF-induced epithelial cell proliferation and migration, offering a potential mechanism that can be responsible for the reduced gingival healing and tissue damage in periodontitis." (PMID 36573202, 2022). "EGF plays a crucial role in inflammation and tissue repair, serving as an important regulator in the process of periodontitis and bone destruction." (PMID 34592884, 2021). "High levels of EGF can be detected in patients with oral diseases and are believed to be closely related to the occurrence and development of periodontitis." (PMID 34592884, 2021). "EGF and genetic factors are important for the regulation of the pathogenesis of periodontitis and GAgP, respectively." (PMID 32477838, 2020). "Abnormal expression of EGF gene has been widely reported in patients suffering from periodontitis, which might be related to the increased activity of collagenase and gelatinase." (PMID 34592884, 2021). "Actually, some studies have reported the association between EGF and periodontitis; however, the results are not consistent in gingival tissues, saliva, gingival crevicular fluid (GCF) and serum." (PMID 32477838, 2020). "In periodontitis, many virulence factors that originate from P. gingivalis (i.e. gingipains, fimbriae, and lipopolysaccharide [LPS]) may disturb the EGF signaling pathway." (PMID 28748038, 2017). "Therefore, our findings suggest that low EGF levels could represent impaired wound healing and resolution of inflammation, also in periodontitis." (PMID 39101637, 2024). "However, until now, little was known about the regulation of the EGF pathway during periodontitis, notably how P. gingivalis and one of its virulent factors (i.e. LPS) could modify the signaling cascade initiated by EGF." (PMID 28748038, 2017). "We present high levels of MMP-12 and low levels of EGF and OLR-1 as interesting candidates that should be further validated in additional cohorts for potential to serve as biomarkers for severe periodontitis." (PMID 39101637, 2024). "The role of EGF and OLR-1 in periodontitis pathogenesis and as possible future biomarkers should be further explored." (PMID 39101637, 2024). "Hence, EGF may be an important mediator in the pathogenesis of periodontitis." (PMID 32477838, 2020).
preeclampsia (10 papers, 2014 to 2025). Preeclampsia is a hypertensive disorder of pregnancy that is characterized by new-onset hypertension with proteinuria presenting after 20 weeks of gestation, and depending on mild or severe forms may initially present with severe headache, visual disturbances, and hyperreflexia. "Recent studies have also associated single nucleotide polymorphism in EGF gene with preeclampsia and low birth weight babies." (PMID 28542650, 2017). "Our results, which show a positive correlation between EGF and preeclampsia features (including the urinary protein-creatinine ratio and systolic and diastolic blood pressure), further support this evidence." (PMID 41006365, 2025). "Decreased expression of placental EGFR has been shown to be associated with obstetrical complications: placental expression of full-length EGFR mRNA transcript is decreased in IUGR while in preeclampsia, placental and plasma EGF levels are reduced." (PMID 29666409, 2018). "Lower levels of EGF in plasma and urine have been reported in women with preeclampsia and IUGR respectively." (PMID 28542650, 2017). "In pregnancy, complications like preeclampsia, shallow invasion of trophoblast cells and low amounts of epidermal growth factor (EGF) have been reported." (PMID 28542650, 2017). "The effect of EGF signaling in preeclampsia is exemplified by HB-EGF (heparin binding EGF like growth factor)." (PMID 25392996, 2014). "Further specific research is needed to determine whether the increase in EGF, HGF, LIF and SCF is a consequence of preeclampsia or if it indicates changes in factors associated with preeclampsia." (PMID 41006365, 2025). "Low levels of EGF and reduced STAT3 phosphorylation are implicated in preeclampsia and IUGR." (PMID 28542650, 2017). "Moreover, reduced EGF levels have been reported for preeclampsia as well as IUGR." (PMID 25983373, 2015). "EGF, HGF and LIF and SCF levels were significantly elevated in preeclampsia." (PMID 41006365, 2025). "In conclusion, we confirmed an increase in EGF, HGF, LIF and SCF in preeclampsia." (PMID 41006365, 2025). "In patients suffering from preeclampsia and IUGR, deciphering the role of EGF in trophoblast invasion and downstream signaling might help better understanding of the significance of reported lower levels of EGF in these conditions." (PMID 28542650, 2017).
Arthritis (9 papers, 2005 to 2025). Inflammation of a joint. "In this study, changes in chondrocyte phenotype and function were determined following treatment with TNF-α and EGF, mediators that contribute to sustaining the inflammatory processes associated with arthritis." (PMID 15642133, 2005). "EGF levels were observed to be elevated in patients with arthritis, whereas patients presenting with edema had significantly higher VEGF concentrations." (PMID 41012652, 2025). "The role of epidermal growth factor (EGF) in the development of articular cartilage and the pathogenesis of arthritis is poorly understood." (PMID 15642133, 2005). "Furthermore, the EGF levels were increased in patients with arthritis and positively correlated with TNF-α expression." (PMID 41012652, 2025). "Using recordings from spinal cord neurons, we were able to show that spinal EGF signaling comes into play when the spinal cord is stimulated by IL-6-trans-signaling, a mechanism involved in the generation of spinal hyperexcitability, e.g., during the development of arthritis." (PMID 39000275, 2024). "Patients with arthritis demonstrated higher frequencies of TLR7+ intermediate monocytes and elevated Epidermal growth factor (EGF) levels, whereas those with edema exhibit increased Vascular endothelial growth factor (VEGF) levels." (PMID 41012652, 2025). "Here we clearly show that arthritogenic antibodies are indeed produced after native COMP immunization that are preferentially directed to the EGF region of the COMP molecule, bind cartilage and induce arthritis in naïve mice." (PMID 22906101, 2012).
cholesteatoma (9 papers, 2013 to 2023). A pathologic process characterized by the proliferation of keratinizing squamous epithelium resulting in the accumulation of keratin and cells in the middle ear and/or mastoid. "In this investigation, we studied the effects of EGF on the proliferation of keratinocytes and EGF-mediated signaling pathways underlying the pathogenesis of cholesteatoma." (PMID 24311896, 2013). "The growth and proliferation of cholesteatoma are closely linked to the upregulation of growth factors, such as epidermal growth factor (EGF) and keratinocyte growth factor (KGF) and its receptors, and cytokines, including IL-1, IL-6, and tumor necrosis factor α (TNF-α)." (PMID 37569652, 2023). "Bone resorption of cholesteatoma is affected by the Ki-67 weighted proliferation index, epidermal growth factor, matrix metalloproteinase-9, bone morphogenic protein, and cytokines such as TNF-alpha." (PMID 36766559, 2023). "Our results are consistent with these findings and demonstrate for the first time that EGFR/PI3K/Akt/cyclinD1 signaling pathway is active in cholesteatoma epithelium and involved in EGF-induced cell proliferation of EACKs." (PMID 24311896, 2013). "Increased EGF expression has been demonstrated in cholesteatoma epithelium, and high EGF levels have also been shown in cholesteatoma debris and subepithelial tissue." (PMID 24311896, 2013). "Epidermal growth factor (EGF) is one of the most important cytokines which has been shown to play a critical role in cholesteatoma." (PMID 24311896, 2013). "It is due to lytic enzymes such as collagenase and inflammatory mediators such as TNF alpha, IL-1,1L-6, IL-7, IFN beta, epidermal growth factor TGF-alpha, and matrix metalloproteinase, released by cholesteatoma matrix and granulation tissue." (PMID 37664290, 2023). "Beyond this growth factors crucial for epidermal growth and wound healing, e.g. EGF, KGF, Epiregulin, bFGF, TGF-β1 and HGF, were upregulated as well in cholesteatoma tissue." (PMID 33627146, 2021). "The expression of the growth factors KGF, EGF, EREG, IGF-2 and HGF was significantly higher in fibroblasts, particularly when derived from cholesteatoma." (PMID 33627146, 2021). "However, the exact mechanisms of EGF in the pathogenesis of cholesteatoma remain unclear." (PMID 24311896, 2013). "Previous studies have shown the expression of EGF and increased expression of EGF receptors (EGFR) in cholesteatoma." (PMID 23852020, 2013). "Moreover, many of these cytokines promote peri-matrix angiogenesis (EGF, PDGF, IL-8, TGFα) and osteoclastogenesis/bone resorption (IL-1, IL-6, PTHrP, receptor activator of nuclear factor kappa-B ligand (RANKL), which are both responsible for cholesteatoma proliferation and local aggressiveness." (PMID 37623440, 2023).
Infertility (9 papers, 2013 to 2025). "The results pointed out that EGF and GnRH-II, as well as other molecules that regulate Twist and N-cadherin expression in decidualized endometrium, are potential therapeutic targets for embryo implantation failure in the treatment of infertility." (PMID 37894950, 2023). "On the other hand, overexpression of EGF induces infertility in transgenic mice." (PMID 26959739, 2016). "It has been shown that submandibular gland ablation leads to decreased circulating EGF and infertility, which could be reversed by EGF in mice, highlighting an important role of EGF in spermatogenesis." (PMID 25880873, 2015). "Likewise, an average concentration of EGF in blood plasma is significantly lower in infertile males." (PMID 24298380, 2013). "Therefore, we concluded that in vitro EGF treatment is an efficient approach to improve the development of human follicles after xenotransplantation, indicating that EGF might be a potent functional stimulator for human infertility treatment." (PMID 32997412, 2020). "A study conducted in 2008 examined epidermal growth factor (EGF) and TGF-β levels in infertile varicocele patients compared to fertile individuals to analyze the association between TGF-β and sperm plasma." (PMID 40524181, 2025). "There are suggestion that infertile women with RIF could benefit from the use of platelet-rich plasma (PRP) containing growth factors (PDGF, EGF, TGFβ, VEGF, HGF, FGF2)." (PMID 36901702, 2023). "Previous studies revealed that AFSCs could ameliorate infertility through the restoration of ovarian function via the activation of various signaling molecules such as VEGF, TGFα and β, epidermal growth factor (EGF), and bone morphogenic protein (BMP)." (PMID 34203240, 2021).
influenza infection (9 papers, 2017 to 2025). "By contrast, in influenza infection, serum EGF and CD40L levels were actually decreased below baseline in patients with more severe disease." (PMID 34529726, 2021). "Group 2 innate lymphoid cells contribute to pulmonary wound healing upon influenza infection via the secretion of Areg, which belongs to the family of epidermal growth factors (EGF) and signals via the EGF receptor (EGFR)." (PMID 29760695, 2018). "The inverse association of EGF with severity is consistent with two smaller studies of acute influenza infection, in which EGF was lower in patients that required intensive care or hospitalization." (PMID 29163498, 2017). "This is also reflected in the fact that core-1 (EGF, GRO, MDC, and sCD40-L) was weakly positively associated with outcome in a cohort of mild influenza infection (FLU09) and was negatively associated with outcome of severe influenza infection (PICFLU)." (PMID 31275311, 2019). "Hence, additional studies are required to determine the bioactive compounds of the EBN against Rab5 protein and study the effects of EBN on initial stages of influenza life cycle with control of the content EGF." (PMID 28056926, 2017). "However, it can be internalized into endocytic vesicles or imported into the nucleus in response to stimuli such as epidermal growth factor (EGF), wogonoside, the cancer environment or influenza infections." (PMID 40248364, 2025). "Moreover, in an influenza infection model, neutrophils can increase the expression of MHC-II and CD11c on monocytes via the secretion of the cytokine EGF." (PMID 39555061, 2024).
leiomyoma (9 papers, 2008 to 2026). A well-circumscribed benign smooth muscle neoplasm characterized by the presence of spindle cells with cigar-shaped nuclei, interlacing fascicles, and a whorled pattern. "Patients with fibroids had uniquely decreased levels of IL-17A (q = 0.023), EGF (q = 0.034), and an elevation of macrophage inflammatory protein-1 beta (MIP-1β) (q = 0.040)." (PMID 38972981, 2024). "Epidermal growth factor (EGF) has been demonstrated to play a crucial role as a local growth factor in regulating leiomyoma growth." (PMID 32251338, 2020). "Leiomyoma growth is influenced by progesterone interaction with some growth factors; it upregulates the EGF (mitogenic) and transforming growth factor- (TGF-)β3 (bimodal action) expression." (PMID 24163697, 2013). "Both epidermal growth factor (EGF) and its receptor (EGFR) have been shown to be expressed in both myometrial and leiomyoma tissues during the secretory phase of the menstrual cycle but EGF mRNA was higher in leiomyoma than myometrium." (PMID 28930160, 2017). "EGF and PDGF seem to increase DNA synthesis and polyploidization in leiomyoma cells through transient activation of kinase pathways." (PMID 24163697, 2013). "Also, EGF activates DNA synthesis in leiomyoma, however EGFR demonstrates equally in both leiomyoma and myometrial smooth muscle cells." (PMID 41514933, 2026). "In addition, estrogens also downregulate epidermal growth factor (EGF) expression but upregulate the expression of EGF-R in both myometrium and leiomyoma cells." (PMID 24163697, 2013). "Interestingly, in monolayer cultures of leiomyoma cells, progesterone was able to increase EGF but not EGFR expression; on the contrary, estrogens increased EGFR expression but did not increase EGF." (PMID 28930160, 2017). "The expression levels of EGF, IGF, TGF-β, and VEGF increased when UPA was used for leiomyoma tissue, but this increase was not statistically significant." (PMID 36313223, 2022).
lymphoma (9 papers, 2009 to 2021). A malignant (clonal) proliferation of B- lymphocytes or T- lymphocytes which involves the lymph nodes, bone marrow and/or extranodal sites. "This study has established that PLD2 up-regulates EGFR expression, as well as EGF-induced Akt activation, in a murine lymphoma cell line." (PMID 27713341, 2010). "A recent study has revealed that increased expression of miR-30c in patients with secondary CNS lymphoma (SCNSL), compared to those with PCNSL, allows the lymphomas to engraft into CNS, by binding to the cadherin EGF LAG seven-pass G-type receptor (CELSR) 3 gene." (PMID 30615673, 2019). "A previous study reported that EGF-induced EGR1 expression could be involved in the down-regulation of matrix metallopeptidase 9 (MMP9) expression in lymphoma cells." (PMID 31635309, 2019). "EGR-1 activation by EGF inhibited MMP9 expression and lymphoma growth." (PMID 22461839, 2012). "Therefore, in order to verify the involvement of EGF and ErbB2 receptors in vp17s clonogenic activity independently of EBV protein expression, we also tested the inhibition of vp17-triggered cell proliferation by AG1478 and AG879 in the EBV-negative BJAB human lymphoma B-cell line." (PMID 33093643, 2021).